KIF26B (kinesin family member 26B)
Description:
Essential for embryonic kidney development. Plays an important role in the compact adhesion between mesenchymal cells adjacent to the ureteric buds, possibly by interacting with MYH10. This could lead to the establishment of the basolateral integrity of the mesenchyme and the polarized expression of ITGA8, which maintains the GDNF expression required for further ureteric bud attraction. Although it seems to lack ATPase activity it is constitutively associated with microtubules (By similarity).
Synonyms: FLJ10157
Tractability: Antibody: the Human Protein Atlas places it where antibodies can reach. PROTAC: UniProt records ubiquitination sites on it.
Gene: Protein-coding gene on chromosome 1 (245,154,985 to 245,709,432, forward strand). Ensembl gene ENSG00000162849.
Subcellular location: Cytoplasm; Cytoplasm, cytoskeleton
Subcellular location (Human Protein Atlas): Microtubules; Primary cilium; Cytokinetic bridge; Plasma membrane
Pathways (Reactome):
Hemostasis: Kinesins
Vesicle-mediated transport: COPI-dependent Golgi-to-ER retrograde traffic
Gene Ontology:
Molecular function: microtubule binding; ATP binding; microtubule motor activity
Biological process: ureteric bud invasion; microtubule-based movement; system development
Cellular component: cytoplasm; cytoskeleton
Genetic constraint (gnomAD): Loss-of-function variants: 63 observed, 136.04 expected, observed/expected ratio (o/e) 0.46, 90% interval 0.38 to 0.57. The upper end of that interval is the gene's LOEUF score, 0.57, which puts it in group 2 of 6, group 1 being the genes least tolerant of losing a copy. Missense variants: 2,813 observed, 2,809.7 expected, observed/expected ratio (o/e) 1, 90% interval 0.97 to 1.03. Synonymous variants: 1,357 observed, 1,212.1 expected, observed/expected ratio (o/e) 1.12, 90% interval 1.07 to 1.17.
Homologues: Orthologues: chimpanzee KIF26B (98% identical), macaque KIF26B (95% identical), guinea pig KIF26B (89% identical), mouse Kif26b (88% identical), rat Kif26b (87% identical), dog KIF26B (87% identical), rabbit KIF26B (83% identical), pig KIF26B (72% identical), tropical clawed frog KIF26B (68% identical), zebrafish kif26ba (63% identical). Paralogues in human: KIF26A (39% identical), KIF14 (11% identical), KIF13B (10% identical), KIF1B (10% identical), KIF13A (10% identical), KIF1A (10% identical), KIF21B (10% identical), KIF7 (10% identical), KIF21A (9% identical), KIF15 (9% identical), KIF16B (9% identical), KIF27 (9% identical), and 29 more.
Diseases named in the same sentence as KIF26B in open-access papers:
KIF26B is named in the same sentence as 40 diseases in open-access papers, as found by Europe PMC text mining. Sharing a sentence is not in itself a finding about the gene and the disease. The quoted sentences say what the papers report.
breast carcinoma (12 papers, 2013 to 2024). "The up-regulation of KIF26B is involved in the occurrence of tumors and is associated with the tumor diameter, metastasis, and poor prognosis in breast cancer, gastric cancer, and colorectal cancer." (PMID 38380081, 2024). "Recent studies have found that KIF26B is associated with the occurrence, progression, and metastasis of various solid tumors, such as hepatocellular carcinoma, breast cancer, and gastric cancer." (PMID 39513664, 2024). "Recently, it has been reported that overexpression of KIF26B is associated with poor prognosis in breast cancer." (PMID 25652119, 2015). "One study found that KIF26B is independently linked to the prognostic outcome in breast cancer." (PMID 32346924, 2020). "KIF26B also promotes the development and progression of breast cancer and plays a key role in breast cancer growth and metastasis." (PMID 35292033, 2022). "Recent studies have reported that KIF26B is involved in gastric cancer and breast cancer as an oncogene." (PMID 35273176, 2022). "Recently, KIF26B has been reported to promote gastric cancer, hepatocellular carcinoma, and breast cancer progression." (PMID 35273176, 2022). "KIF2A, KIF14 and KIF26B were found overexpressed in lymph nodes-positive breast cancer patients indicating putative impacts on tumor metastasis." (PMID 32322170, 2020). "It has been confirmed that KIF26B regulates cell invasion in breast cancer through driving epithelial-mesenchymal transition (EMT)." (PMID 32536821, 2020). "KIF26B also plays an important role in kidney development and is involved in the development and progression of some types of tumors, including breast cancer, esophageal adenocarcinoma, and colorectal adenomatous polyposis." (PMID 25652119, 2015). "Here, we demonstrate that both KIF26B mRNA and protein are overexpression in breast cancer tissues by RT-qPCR and western blot." (PMID 23585914, 2013). "In the present study, we found that both KIF26B mRNA and protein were upregulated in primary breast cancer tissues." (PMID 23585914, 2013). "Immunohistochemistry was performed to determine the KIF26B expression in 200 paraffin-embedded primary breast cancer tissues." (PMID 23585914, 2013). "In 27 of 30 cases, KIF26B mRNA was upregulated in primary breast cancer tissue, compared to the adjacent normal breast tissues (P<0.001)." (PMID 23585914, 2013). "To examine expression of KIF26B in breast cancer tissues, we firstly detected the mRNA and protein levels in 30 paired primary breast cancer tissues and the corresponding adjacent normal tissues using RT-qPCR and western blot." (PMID 23585914, 2013). "Furthermore, high expression of KIF26B in breast cancer was significantly associated with other malignant tumor characteristics, such as larger tumor size, higher histological grade and lymph node metastasis, indicating that KIF26B might be served as a hallmark of malignant tumors." (PMID 23585914, 2013). "Consistently, in 26 of 30 cases, the protein levels of KIF26B in primary breast cancer tissues were dramatically higher than those in the normal breast tissues by western blot." (PMID 23585914, 2013). "We next evaluated the KIF26B expression and other clinicopathologic factors on prognosis of breast cancer, using univariate analyses." (PMID 23585914, 2013). "In this study, we examined KIF26B expression in breast cancer tissues, analyzed the relationship between KIF26B expression and clinicopathological factors, and determined the potential role of KIF26B in breast cancer prognostic prediction." (PMID 23585914, 2013). "Our data indicated that KIF26B was remarkably overexpression in breast cancer and could be served as a potential biomarker of prognosis." (PMID 23585914, 2013). "Collectively, our study demonstrated that KIF26B was overexpression in breast cancer and could be served as a potential prognostic marker." (PMID 23585914, 2013).
breast carcinoma (continued). "Moreover, our study provides the clinical evidence that KIF26B is independently prognostic for outcome in breast cancer." (PMID 23585914, 2013). "In addition, multivariate analysis indicated that KIF26B is an independent prognostic for outcome in breast cancer (HR, 2.356; 95%CI, 1.268–4.378; P = 0.007)." (PMID 23585914, 2013). "In conclusion, we showed that KIF26B is overexpression in breast cancer tissues." (PMID 23585914, 2013). "Moreover, the Kaplan-Meier analysis indicated that breast cancer patients with high KIF26B expression had a shorter survival than those with low KIF26B expression." (PMID 23585914, 2013). "High level of KIF26B expression (KIF26Bhigh; score > median) was seen in 94 of 200 breast cancer." (PMID 23585914, 2013). "Furthermore, Cox regression analysis suggested KIF26B as an independent prognostic factor, indicating that KIF26B may be an important modulator involved in breast cancer development." (PMID 23585914, 2013).
hepatocellular carcinoma (9 papers, 2019 to 2025). A malignant tumor that arises from hepatocytes. "Downregulation of KIF26B inhibits the viability, proliferation and invasiveness of hepatocellular carcinoma cells." (PMID 35292033, 2022). "When we checked the literature, we also found that KIF26B can promote the progression of hepatocellular carcinoma by activating the PI3K/AKT pathway." (PMID 35866054, 2022). "For example, studies have shown that the expression of KIF3B and KIF26B is significantly increased in hepatocellular carcinoma (HCC) tissues and HCC cell lines, and the knockout of KIF3B or KIF26B stimulated apoptosis of cancer cells and reduced malignant characteristics of tumors." (PMID 40964093, 2025). "In hepatocellular carcinoma (HCC), KIF26B activation was suggested to promote cancer progression by activating the phosphatidylinositol 3-kinase (PI3K) and Akt/Protein Kinase B (PI3K/Akt) signaling pathway." (PMID 33717105, 2021). "Kinesin family member 26B (KIF26B) is unveiled acted as important role in many solid tumors, however, the function of KIF26B in hepatocellular carcinoma (HCC) is unclear." (PMID 31388332, 2019).
gastric cancer (8 papers, 2018 to 2024). A primary or metastatic malignant neoplasm involving the stomach. "Increased expression of KIF26B in gastric cancer is associated with tumour size, lymph node metastasis positivity or distant metastasis and poor prognosis." (PMID 35292033, 2022). "KIF26B promotes gastric cancer proliferation and metastasis by activating the VEGF pathway." (PMID 29706624, 2018). "The data indicated that kinesin family member 26 B (KIF26B) was one of the most upregulated genes in metastatic human gastric cancer (GC) tissues." (PMID 33505901, 2020). "Recent studies have reported that KIF26B is overexpressed in BRCA, ECA, colorectal cancer, and gastric cancer." (PMID 35359341, 2022).
colorectal cancer (7 papers, 2015 to 2024). A primary or metastatic malignant neoplasm that affects the colon or rectum. "In colorectal cancer, the copy number of KIF26B gene was significantly associated with susceptibility to colorectal adenoma." (PMID 35866054, 2022). "KIF26B is associated with poor prognosis in breast and colorectal cancers." (PMID 28945760, 2017). "KIF26B is highly expressed in colorectal cancer tissues, and the proliferative capacity of colorectal cancer cells was significantly reduced after KIF26B was silenced." (PMID 35866054, 2022). "The present study investigated the expression and clinical significance of kinesin family member 26B (KIF26B) in colorectal cancer (CRC)." (PMID 25652119, 2015). "Forty paired specimens were analyzed for KIF26B mRNA and protein expression, 30 (75%) colorectal cancers showed a more than 2-fold increase in KIF26B mRNA levels compared with adjacent normal mucosa." (PMID 25652119, 2015). "However, F. nucleatum via activation of YAP signalling and subsequent transcriptional regulation of METTL3, results in KIF26B reactivation and ultimately metastases of colorectal cancer cells." (PMID 37322598, 2023). "Studies have shown that high KIF26B expression in colorectal cancer tissues can increase the proliferation, migration, and invasiveness of colorectal cancer cells and increase tumour depth and lymph node metastasis and that high KIF26B expression is closely related to poor prognosis." (PMID 35292033, 2022). "KIF26B, a member of the kinesin (KIF) family, is a known oncogene which promotes metastasis in gastric cancer and colorectal cancer." (PMID 37322598, 2023).
ovarian carcinoma (5 papers, 2020 to 2026). A malignant neoplasm originating from the surface ovarian epithelium. "Bioinformatics analysis revealed that KIF26B was highly expressed in ovarian cancer tissues and was associated with poor clinical characteristics." (PMID 41751488, 2026). "In this study, we evaluated the role of KIF26B in drug-resistant ovarian cancer and the underlying mechanisms." (PMID 41751488, 2026). "Overall, our results indicate that KIF26B is crucial for ovarian cancer progression and chemotherapy resistance, likely through SLC7A11 regulation." (PMID 41751488, 2026). "KIF26B, a kinesin family protein, is involved in various cancers, but its role in ovarian cancer and chemotherapy resistance is unclear." (PMID 41751488, 2026). "KIF26B knockdown significantly reduced paclitaxel resistance in ovarian cancer cells, inhibited cell proliferation, and promoted apoptosis." (PMID 41751488, 2026). "Apart from that, rs6690829, another IV for N-acetylalanine, lies on gene KIF26B, whose up-regulation correlates with cancer cell function in ovarian cancer." (PMID 38737546, 2024). "To clarify the biological function of KIF26B, we constructed a cisplatin resistant ovarian cancer cell line A2780 (A2780/DDP)." (PMID 38696071, 2024). "The CCK-8 assay and clonogenic assay showed that knockdown of KIF26B expression significantly reduced ovarian cancer cell proliferation." (PMID 38696071, 2024). "KIF26B was selected to construct a prognostic model from the identified 33 prognosis-related genes, and high expression of KIF26B predicted poorer prognosis in ovarian cancer." (PMID 38696071, 2024). "Upregulation of KIF26B increased proliferation and migration in ovarian cancer cell lines." (PMID 32133296, 2020). "The IHC showed that the protein level of KIF26B in ovarian cancer was significantly higher than that in normal ovarian epithelial tissues." (PMID 38696071, 2024). "Additionally, our analyses revealed a negative correlation between KIF26B and SLC7A11 in ovarian cancer, particularly in chemoresistant tissues." (PMID 41751488, 2026).
colon cancer (2 papers, 2024). "CT variant was found significantly more frequently within the CEA elevated patients, implying it may affect not only the esophagogastric cancer prognosis but also the molecular behavior of other CEA producing malignancies in a similar genetic pattern as KIF26B non-coding RNA in colon cancer." (PMID 38339289, 2024). "For instance, in colon cancer, downregulation of m6A levels reduces YTHDF2-dependent mRNA degradation, leading to increased expression of its target gene, KIF26B, and facilitating colon cancer progression and metastasis." (PMID 38576024, 2024).
esophageal adenocarcinoma (2 papers, 2015 to 2022). A malignant tumor with glandular differentiation arising predominantly from Barrett mucosa in the lower third of the esophagus. "KIF26B was the more frequent mutation (>10%) in patients with esophageal adenocarcinoma, UCS (uterine carcinosarcoma), UCEC, BRCA, SKCM, LIHC, and STAD." (PMID 35359341, 2022). "Increased amplification of KIF26B is also associated with higher progression stage of esophageal adenocarcinoma." (PMID 25652119, 2015).
lung cancer (2 papers, 2024 to 2025). A malignant neoplasm involving the lung. "Furthermore, KIF26B silencing led to the downregulation of vimentin and N-cadherin, upregulation of E-cadherin, and diminished Wnt/β-catenin pathway activity, implicating KIF26B as a positive regulator of EMT and Wnt/β-catenin signalling in lung cancer cells." (PMID 40002279, 2025).
osteosarcoma (2 papers, 2019 to 2023). A usually aggressive malignant bone-forming mesenchymal neoplasm, predominantly affecting adolescents and young adults. "Previous studies have proved that miR-20a-5p suppressed SDC2 and KIF26B, leading to a reduction in the multi-drug resistance of osteosarcoma." (PMID 36769824, 2023). "Other study demonstrated that KIF26B played important role in multi-drug resistance in osteosarcoma." (PMID 31388332, 2019).
asthma (1 paper, 2023). "KIF26B has been identified as an oncogene in several tumors and there is a study examining the relationship between early-life tobacco smoke exposure and genetic variants in this gene on bronchial hyper-responsiveness in asthma." (PMID 36834337, 2023).
cutaneous melanoma (1 paper, 2022). A primary melanoma arising from atypical melanocytes in the skin. "In SKCM (cutaneous melanoma) and THYM (thymoma), KIF26B was highly expressed in tumor tissues (P < 0.05)." (PMID 35359341, 2022).
kidney malformations (1 paper, 2020). "Many studies suggest that CNVs contribute to the etiology of RHD and implicate the genes within the CNV loci (e.g., PAX2, HNF1B, KIF26B, which are associated with kidney defects), that are detected in up to 10% of individuals with kidney malformations." (PMID 32211073, 2020).
medulloblastoma (1 paper, 2022). A malignant, invasive embryonal neoplasm arising from the cerebellum. "The PCR results of our study showed that KIF26B is highly expressed in medulloblastoma, and its high expression is associated with a high clinical stage." (PMID 35866054, 2022). "In order to select a suitable cell line for the experiment, we first determined the expression of KIF26B in several medulloblastoma cell lines relative to the normal cell." (PMID 35866054, 2022). "First, we detected the mRNA expression level of KIF26B in medulloblastoma tissues and adjacent normal tissues and found that KIF26B is highly overexpressed in tumor sample and patients with high KIF26B expression often have worse prognosis." (PMID 35866054, 2022). "This indicated that the effect of KIF26B on medulloblastoma cells is indeed carried out through the PI3K pathway." (PMID 35866054, 2022). "At the same time, the clone formation experiment also suggests that KIF26B can promote the clone formation ability of medulloblastoma cells." (PMID 35866054, 2022). "The experimental results showed that compared with the control group, the migration and invasion ability of medulloblastoma cells in the KIF26B silenced group were significantly inhibited, and the difference was statistically significant (p < 0.01)." (PMID 35866054, 2022). "KIF26B promotes the malignant progression of medulloblastoma by affecting the expression of phosphorylation of key proteins in the PI3K/AKT signaling pathway." (PMID 35866054, 2022). "These experimental results showed that KIF26B can promote the malignant progression of medulloblastoma." (PMID 35866054, 2022). "In order to further explore the possible mechanism of KIF26B promoting the malignant progression of medulloblastoma, we first performed an enrichment analysis of the gene set that is significantly related to the expression of KIF26B." (PMID 35866054, 2022). "The tissue samples were first used to analyze the expression of KIF26B in the tumor and adjacent normal tissue of 30 patients with medulloblastoma." (PMID 35866054, 2022). "At last, the expression of PI3K/AKT pathway proteins was studied to explore the mechanism of KIF26B in medulloblastoma." (PMID 35866054, 2022). "In order to further explore the mechanism of KIF26B promoting the malignant phenotype of medulloblastoma, we analyzed and collected gene sets that were significantly positively correlated with KIF26B expression and submitted them to the KEGG pathway for enrichment analysis." (PMID 35866054, 2022). "Based on these studies and the bioinformatics analysis, it is speculated that KIF26B is closely related to the malignant process of medulloblastoma." (PMID 35866054, 2022). "In view of the high expression of KIF26B in medulloblastoma tumor tissues, we speculate that KIF26B may be involved in the malignant progression of medulloblastoma." (PMID 35866054, 2022). "Knockdown the expression of KIF26B could significantly impair the proliferation and migration of medulloblastoma cells." (PMID 35866054, 2022). "Therefore, KIF26B is probably involved in the occurrence and development of medulloblastoma." (PMID 35866054, 2022). "In addition, KIF26B may participate in the malignant progression of medulloblastoma through PI3K/AKT signaling pathway." (PMID 35866054, 2022). "Therefore, our experimental results suggest that KIF26B is a potential target for medulloblastoma." (PMID 35866054, 2022). "However, there is no relevant research on the expression and role of KIF26B in medulloblastoma." (PMID 35866054, 2022).
microcephaly (1 paper, 2019). A congenital or acquired developmental disorder in which the circumference of the head is smaller than normal for the person's age and sex. "However, because ofthe presentation of microcephaly in the patients with intactAKT3 gene, the other candidate genes such as NLRP3,HNRNPU, SMYD3, and KIF26B have been suggestedto cause microcephaly." (PMID 31210441, 2019).